FGFR2 (fibroblast growth factor receptor 2)
Diseases named in the same sentence as FGFR2 in open-access papers (continued):
Sharing a sentence is not in itself a finding about the gene and the disease.
tumor (continued). "Although the role of FGFs in PDAC has been controversial, a set of good-prognostic LR pairs including FGF7, FGF10, and FGFR2 is proposed to exert a tumor suppressive function via reduced oxidative stress and activation of immune surveillance." (PMID 34522794, 2021). "Previous studies on FGFR2 in tumors are limited to individual tumor types and/or to limited sample sizes." (PMID 33968743, 2021). "Our data indicated that FGFR2 activation in mammary tissues induced tumor formation in 30.13% (22/73) of all mice and the median time was 22 months." (PMID 34514747, 2021). "Preclinical data have showed a strong antiproliferative activity of this compound in a panel of human NSCLC cell lines harbouring FGFR aberrations and tumour growth inhibition in a gastric cancer FGFR2-amplified mouse xenograft model." (PMID 34068816, 2021). "Paraffin-embedded tumor samples from formalin-fixed surgical or biopsy specimens of patients with advanced/recurrent BTC were analyzed for positivity of FGFR2 rearrangement by fluorescent in situ hybridization (FISH)." (PMID 33106918, 2021). "Next, we evaluated the expression level of FGFR2 protein in patient’s surgical samples with TACC2-FGFR2 using immunohistochemistry (IHC), finding increased FGFR2 expression in tumor area compared to adjacent normal surface epithelial area." (PMID 34551773, 2021). "GSEA results using the C5 reference gene set identified signaling by FGFR in disease, signaling by Robo receptors, signaling by FGFR2 in disease, FGFR2 alternative splicing, FGFR2 mutant receptor activation, and tumor differentiated well vs poorly up." (PMID 33985510, 2021). "On a tumor slice culture platform, the combination of FGFR2 inhibition plus immune checkpoint demonstrate strong therapeutic efficacy within 4 days." (PMID 34514747, 2021). "MiR-494 has been found to act as a tumor suppressor and to restore lapatinib sensitivity and inhibit formation of cancer-initiating cells (CICs) via reducing expression of FGFR2 in HER2-positive, FGFR2 overexpressing and lapatinib resistant GC cell cultures." (PMID 33801049, 2021). "Of note, FGFR2 expression was highest in the patient’s tumor than in all other tumors from the TCGA cohort (log2 fold change = 2.01), whereas the expression levels of different tyrosine kinases, including FGFR1, 3, and 4, was in the range of the other samples." (PMID 34480077, 2021). "Meanwhile, according to the interquartile range, the spread of FGFR2 expression varied in several tumor types more than others." (PMID 33968743, 2021). "A current challenge for molecular tumor boards (MTB) is to predict the functional consequences of such FGFR2 alterations to guide potential treatment decisions." (PMID 34480077, 2021). "The concomitant blockade of VEGF signaling with the VEGFR2-blocking monoclonal antibody and FGF signaling by adenovirus-delivered soluble form of FGFR2 (FGF-trap) significantly reduced tumor burden and vessel density compared to the anti-VEGFR2 alone." (PMID 33804681, 2021). "After in silico investigation of the alterations and identification of activated FGFR2 downstream targets in tumor specimens by immunohistochemistry and transcriptome analysis, the MTB recommended treatment with an FGFR-inhibiting tyrosine kinase inhibitor." (PMID 34480077, 2021). "On the contrary, the overexpressed SNORD126 in HCC was proved to function as the tumor-promoting snoRNA through increasing fibroblast growth factor receptor 2 (FGFR2) expression and then activating the PI3K-AKT pathway." (PMID 34195281, 2021). "In another case, a patient presenting with an FGFR2–SORBS1 gene fusion achieved a maximum tumour burden reduction of 68% from baseline to third-line treatment with the pan-FGFR inhibitor futibatinib after developing resistance to infigratinib and Debio 1347." (PMID 33268819, 2021).
tumor (continued). "We systematically profiled abnormal FGFR2 expression, methylation, alteration, and clinical implications across 32 TCGA cancer types covering over 10,000 tumor samples." (PMID 33968743, 2021). "We also confirmed that LLC2B has the ability to recognize the FGFR2 protein and FGFR2-positive tumor cells and tissue in vitro and in vivo." (PMID 34440055, 2021). "At least nine FGFR2 splice variants are reported, expression of which varies even within the same tumor type, while FGFR2 contains at least one and perhaps as many as three more exons than other FGFRs." (PMID 34007277, 2021). "Preclinical studies suggested that dysregulation of the stemness-related FGFR2 signaling pathway plays a key role in the oncogenic processes of the immune-desert UPS and FGFR2 pharmacological inhibition impaired the tumor growth of patient derived xenograft." (PMID 34299136, 2021). "FGFR2, VEGF, TRAIL-R1, and TRAIL-R2 are known to be associated with carcinogenesis, and some of these tumor tissue biomarkers did help refine recurrence prediction in individuals undergoing surgical resection for HCC." (PMID 31940413, 2020). "They showed that the FGFR2 gene fosters BC by maintaining a population of cells that have the capacity of initiating tumours, namely Cancer Stem Cells (CSCs) or tumor-initiating cells (TICs)." (PMID 32188012, 2020). "We and others have shown mechanistically that FGFR2 promotes hormone-independent tumor growth and resistance to endocrine therapies." (PMID 32971804, 2020). "Overexpression of miR-381 in OSCC cell lines inhibits cell proliferation by increasing the proportion of G1/G0-phase cells, indicating that miR-381 acts as a tumor suppressor, possibly because miR-381 targets FGFR2 and downregulates it." (PMID 33324542, 2020). "Target 2, which resided 1.06 mm from target 1, exhibited tumor cells containing both strongly amplified MET and CCND1, 3 to 4 copies of EGFR, 3 to 4 copies of FGFR2, and loss of both copies of the genes encoding PD-L1/PD-L2." (PMID 32338752, 2020). "The 2D in vitro tumor growth rates of Mock and FGFR2-Fc–expressing tumor cells were similar to each other." (PMID 32076044, 2020). "In vivo tumor growth after the inoculation of mixtures of Mock and FGFR2-Fc–expressing tumor cells was similar to that of Mock cells alone in the Renca model, but was slower than that of Mock cells alone in the B16F10 model." (PMID 32076044, 2020). "In this context, it has been shown that FGFR1 expression increases as the tumor progresses from benign to malignant, whereas FGFR2 levels in human gliomas gradually diminish." (PMID 33352931, 2020). "The copy-number stable tumor contained multiple mutations affecting key genes in the PI3K pathway, such as PTEN, FGFR2 and two deleterious mutations in the PIK3R1 gene." (PMID 32873813, 2020). "In vivo studies revealed that FGFR2 inhibition slowed tumor growth and augmented the cytotoxic effects of cisplatin." (PMID 31948066, 2020). "We performed ISH to confirm the results of ERBB2, FGFR1, and FGFR2 status in the two lesions, and we confirmed amplification in either tumour #1 or tumour #2." (PMID 31929516, 2020). "For example, TAMs secrete TGF-β, vascular endothelial growth factor (VEGF), fibroblast growth factor 2 (FGF2), FGF10, fibroblast growth factor receptor 2 (FGFR2), and several MMPs to support tumor growth and immune protection." (PMID 33224886, 2020). "Several patients experienced clinical benefit with tumor mutations in cKIT, CSF-1R, PDGFRα, PDGFRβ, VEGFR1, VEGFR2, FLT3, FGFR2, RET, and TrkA." (PMID 32292573, 2020). "Pharmacodynamicanalyses showed that a plasma target of 22 nM of total INCB054828 was sufficient toinhibit FGFR2 autophosphorylation by 50% in the tumor." (PMID 32315352, 2020). "Compared with FGFR1 and 3, positive ratios of FGFR2 or 4 were generally lower in most of the tumor types, except in CHOL and LIHC." (PMID 32596330, 2020).
tumor (continued). "Inoculation with a mixture of VEGFR2-Fc– and FGFR2-Fc–expressing tumor cells showed further significant delay of in vivo tumor growth compared with inoculation with a mixture of Mock and VEGFR2-Fc–expressing tumor cells." (PMID 32076044, 2020). "Cell culture supernatants of the Mock and FGFR2-Fc–expressing tumor cells were collected to assess the specific binding of FGFR2-Fc to FGF1 and FGF2." (PMID 32076044, 2020). "As to the functional role, depletion of FGFR2 leads to suppression of tumor growth by inducing G1 phase cycle arrest and apoptosis." (PMID 32934314, 2020). "Among these 5 cases, we detected tumor-specific FGFR2 translocations in > 50% of tumor cells in 4 cases and in 5% of tumor cells in the tumor harboring the FGFR2-UBP1 fusion." (PMID 32315234, 2020). "Such inhibition of tumour growth was followed by a significant reduction of protein FGFR2 phosphorylation together with Erk1/2 activation." (PMID 32188012, 2020). "We and others have recently showed that in BCa, FGFR2 is a major transducer of signals between tumour and its microenvironment (TEM), mediating interactions between TEM and hormone receptor-dependent pathways." (PMID 33297384, 2020). "The most striking result was the difference in nuclear expression of FGFR2 between the different tumour samples." (PMID 32522271, 2020). "Consistent with the results of the HUVEC tube formation assay in vitro, tumor angiogenesis was strongly suppressed in tumors formed from a mixture of VEGFR2-Fc– and FGFR2-Fc–expressing tumor cells compared with the other combinations above." (PMID 32076044, 2020). "To date, the most promising results have been reported for patients whose tumours harbour IDH-mutations, FGFR2 fusions or BRAFV600E mutations (Table A1)." (PMID 32932925, 2020). "Preclinical and experimental work has validated the tumor-promoting role of FGFR2 in tumorigenesis and metastasis of GC." (PMID 32934314, 2020). "Previously, we demonstrated that FGF9 signaling through FGFR2-stimulated cell proliferation and tumor growth in MA-10 cells." (PMID 33172093, 2020). "The adjacent tumour tissue showed higher expression of FGFR2 as compared with the normal adrenal cortex." (PMID 32522271, 2020). "The target profile of Infigratinib/Bevacizumab is likely to confer antitumor activity in HCC tumor models that express high levels of FGFRs, particularly FGFR-2 and 3, which significantly inhibit tumor progression and invasion to prolong the survival of mice." (PMID 33321903, 2020). "We further investigated the effect of FGFR2 on ESCC progression in vivo using a xenograft tumor nude mouse model." (PMID 31523191, 2019). "We next compared the relative expression of FGFR2 mRNA levels in normal tissues and tumor tissues using NCBI Gene Expression Omnibus (GEO) datasets." (PMID 30837551, 2019). "Given the expressional differences between normal and tumor samples for FGFR2 isoforms and ESRP1, we next crossed these data with several clinico-pathological features made available by the TCGA consortium." (PMID 31881796, 2019). "The loss of the homeostasis-promoting intrinsic FGFR2 signaling and concurrent gain of ectopic FGFR1 expression in epithelial tissues of a variety of organs are found associated with tumor progression." (PMID 30761180, 2019). "In a comparativegenomic analysis of HPV-positive and HPV-negative tumours, the former showedmutations in FGFR2 and MLL3, among others." (PMID 31188922, 2019). "More than half (183/348—53%) of tumor samples presented FGFR2-IIIb and ESRP1 overexpression and FGFR2-IIIc under-expression in comparison to the median expression of normal stomach samples." (PMID 31881796, 2019). "Derazantinib demonstrated encouraging anti-tumour activity and a manageable safety profile in patients with advanced, unresectable iCCA with FGFR2 fusion who progressed after chemotherapy." (PMID 30420614, 2019).
tumor (continued). "Herein, we explore the (epi)genetic regulation and expression pattern of FGFR2, its isoforms and splicing regulator ESRP1, in normal and tumor stomach samples, and potential associations with clinico-pathological and survival data." (PMID 31881796, 2019). "In the DNET, considered as a benign grade I tumour, we found high expression levels of ErbB3, FGFR2, FOLH1 and AXL." (PMID 31747973, 2019). "Somatic mutations in the genes encoding VEGFR2, FGFR1, FGFR2, FGFR3, and KRAS were identified in the patient's tumor tissue." (PMID 30792968, 2019). "Functional studies demonstrated that FGFR2-ADC administration leads to a significant tumor growth inhibition or tumor regression of cell line-based or patient-derived xenograft models of human gastric or breast cancer." (PMID 31242658, 2019). "A previously published report suggested a tumor-suppressive function of the FGFR2 signaling in the skin." (PMID 31167513, 2019). "It seems that stromal fibroblasts mainly intervene through the expression patterns of two isoforms of fibroblast growth factor receptor type 2 (FGFR2)—FGFR2-IIIb and FGFR2-IIIc—in tumor cells, and fibroblasts express the same type of FGFR2 isoform." (PMID 31109060, 2019). "First, we used Western blotting to investigate the expression levels of DDX6, HER2, and FGFR2 in 20 GC clinical tumor samples." (PMID 29987267, 2018). "Loss of mutations from primary tumor to metastases were identified in case 5 (PDGFRA) and case 9 (FGFR2)." (PMID 29731974, 2018). "In our study, tumor areas with high FGFR2 gene amplification also showed high levels of FGFR2 mRNA expression." (PMID 28852882, 2018). "Of note, the authors highlighted a considerable intra-tumor heterogeneity for FGFR2 amplification and poor concordance between FGFR2 amplification/polysomy and FGFR2 expression, suggesting the need for alternative biomarker testing." (PMID 30008616, 2018). "For the samples with moderate and strong FGFR2 expression higher than score 2, we determined the percentage of tumor cells showing FGFR2 mRNA." (PMID 28852882, 2018). "The tumor suppressor epithelial isoform of the fibroblast growth factor receptor 2 (FGFR2b) induces human keratinocyte early differentiation." (PMID 29752438, 2018). "Unexpectedly, additional deletion of endothelial Fgfr1 and Fgfr2 in Vegfr2 heterozygous mice shows similar tumor growth and angiogenesis as the Vegfr2 heterozygous mice." (PMID 30283071, 2018). "To enroll patients onto MET and FGFR2 amplification matched trials, we validated these alterations in available corresponding patient tumor tissue." (PMID 32913970, 2017). "The clinical value of these findings was supported by an observed response to an FGFR inhibitor, BGJ398, in a patient’s tumor that carried FGFR2 F276C." (PMID 30761385, 2017). "The larger number of reads supporting the gene fusion indicated that the fused form of FGFR2 exhibited elevated expression in the resistant tumor." (PMID 28122360, 2017). "Preclinical studies demonstrated potent inhibition of tumour growth in FGFR pathway-activated models, including in FGFR2-driven (amplification/fusion/mutation) tumour xenografts." (PMID 28972963, 2017). "As added confirmation of our copy number results, we used a highly sensitive ddPCR assay to assess the FGFR2 status of the primary tumor, ovarian metastases, and matched normal gastric tissue." (PMID 28629429, 2017). "The formalin-fixed paraffin-embedded (FFPE) samples of a total of 327 patients had a tumor portion of > 70%, and were adequate for analyzing the relationship between FGFR2 amplification and clinicopathologic factors." (PMID 27802183, 2017).
tumor (continued). "CNVs in tumour cells also enhance proliferation, albeit at the expense of the host; for example, copy number amplification can drive tumour growth (e.g., of FGFR2 or CDK4) or mediate drug resistance (e.g., of DHFR, KRAS or BRAF)." (PMID 28654659, 2017). "For qPCR of the FGFR2 gene in tissues with a tumor portion of < 70%, microdissection will be needed." (PMID 27802183, 2017). "By using in vitro studies, we show that the F276C FGFR2 variant is sensitive to BGJ398, a pan-FGFR inhibitor, which was also reflected clinically in the response of a patient’s tumor when treated with BGJ398 as part of a clinical trial." (PMID 30761385, 2017). "An FGFR2-IIIb-specific antibody, GP369, has been shown to inhibit the proliferation of human cancer cell lines and tumor xenografts with amplified or activated FGFR2 signaling." (PMID 28030802, 2017). "Bioinformatic software designed to predict SCNA from tumor samples confirmed the FGFR2 amplification from sequencing data, and findings were verified by chromosomal microarray and fluorescence in situ hybridization (FISH)." (PMID 28835367, 2017). "In the present study, high FGFR2 expression significantly correlated with tumor progression and survival in only DGC, and such expression was likely to be associated with peritoneal dissemination." (PMID 28056982, 2017). "Knockdown of FGFR2 expression in ESRP1-overexpressing Caco-2 cells reduced the size of the soft agar colonies showing that FGFR2 participated in anchorage-independent tumor growth." (PMID 28052020, 2017). "Although FGFR2 amplification was correlated with FGFR2 expression, only the latter was strongly correlated with tumor depth and patient outcome." (PMID 26933914, 2016). "Immunofluorescence (IF) staining verified a substantial KD of FGFR2 or CD44 following oral administration of Dox during tumor growth in tumor cell-injected mice and a subsequent delay in tumor growth (respectively)." (PMID 27107424, 2016). "Primary tumour samples from 152 stage I–III BCa patients were examined for FGFR2 and RSK2 gene and protein expression." (PMID 27476168, 2016). "Meanwhile, the expression of fibroblast growth factor receptor-2 (FGFR2), a downstream effector of p63, was upregulated in tumor cells." (PMID 27066782, 2016). "FGFR2-myc-expressing cells formed more tumor spheres and grew more progressive tumors in nude mice and NSG than the vector control." (PMID 27107424, 2016). "The significantly mutated cancer-related genes that were identified in tumor tissue included EGFR, KDR, FGFR2, and RET." (PMID 27149458, 2016). "We successfully extracted the tumor DNA from 145 cases with sufficient tumor area on the slides (145/176 = 82%), and assayed the FGFR2 copy number in 140 cases (140/145 = 97%)." (PMID 26933914, 2016). "Gene mutations in the genes encoding EGFR, FGFR2, KDR, and RET were discovered in the patient's tumor tissue by whole exome sequencing and the patient was treated with a combination of the targeted drugs cetuximab and sunitinib." (PMID 27149458, 2016). "In this study, we assessed the cooperative role of CD44 and FGFR2 in cross regulation and GC tumor initiation." (PMID 27107424, 2016). "Most of all, FGFR2 KD in vivo suppressed tumor growth in mice as shown by multiple independent experimental replicates." (PMID 27107424, 2016). "One tumor exhibited a high level of FGFR2 amplification with a low level of EGFR and KRAS amplification." (PMID 27014419, 2016). "Each positive tumor cells between FGFR2-overexpression and HER2-overexpression were mutually exclusive." (PMID 27014419, 2016). "Selective inhibition of FGFR2 sufficiently suppressed tumor cell proliferation through de-phosphorylation of AKT and ERK." (PMID 26933914, 2016). "The shRNA set 1-mediated stable knockdown (KD) of FGFR2 resulted in suppressed cell growth in vitro, reduced tumor growth in nude mice (n = 10), and reduced tumor sphere formation in vitro." (PMID 27107424, 2016).